SMYD2 (SET and MYND domain containing 2)
Diseases named in the same sentence as SMYD2 in open-access papers (continued):
Sharing a sentence is not in itself a finding about the gene and the disease.
colorectal cancer (9 papers, 2016 to 2024). A primary or metastatic malignant neoplasm that affects the colon or rectum. "Taken together, these data demonstrated that Smyd2 deficiency reduces murine colon tumor growth in vivo and that this process is conserved in human colorectal cancer cells." (PMID 35022391, 2022). "In colorectal cancer, SMYD2 increases RNA-binding activity via the monomethylation of K422 on HNRNPK, thereby influencing the stability of EGF-like domain multiple 7 (EGFL7) mRNA." (PMID 39482529, 2024). "In order to investigate a potential contribution of SMYD2 in colorectal cancer (CRC) development, we initially detected the expression pattern of SMYD2 in colon tumors in murine samples." (PMID 35022391, 2022). "Moreover, SMYD2 overexpression has been confirmed in colorectal cancer tissues from patients, and SMYD2 knockdown reduced cell proliferation in xenograft and in vitro models." (PMID 39482529, 2024). "Furthermore, SMYD2-mediated regulation of the Erb-B2 receptor tyrosine kinase 2 (ERBB2)/fucosyltransferase 4 (FUT4) signaling pathway controls colorectal cancer growth." (PMID 39482529, 2024). "Although SMYD2 has been shown to play critical roles in tumor development in several types of cancers, the functional role of SMYD2 in colorectal cancer is largely unknown." (PMID 35022391, 2022). "In the present study, we investigated whether and how SMYD2 might contribute to colorectal cancer." (PMID 35022391, 2022). "In terms of direct targets, SMYD2 regulates the level of H3K36me2 on Mex-3 RNA-binding family member A (MEX3A), thereby controlling the growth of colorectal cancer by regulating the target of MEX3A, namely, caudal type homeobox 2 (CDX2)." (PMID 39482529, 2024). "Interestingly, Smyd-2 has been shown to promote tumor growth in Ovarian Clear-Cell Carcinoma (OCCC) and Colorectal Cancer (CRC) by inhibiting TNF-induced apoptosis." (PMID 39682718, 2024).
leukemia (9 papers, 2016 to 2023). A malignant (clonal) hematologic disorder, involving hematopoietic stem cells and characterized by the presence of primitive or atypical myeloid or lymphoid cells in the bone marrow and the blood. "PCR analysis of secondary leukemia samples showed elimination of the mutant allele, indicating a competitive disadvantage of Smyd2-deleted cells in vivo." (PMID 27655694, 2016). "Low survival rates in leukemia patients are associated with the high expression level of SMYD2." (PMID 27790639, 2016). "This suggests that the continued proliferation of gastric tumor cells is connected to SMYD2 function and, as is the case for some leukemias, highlights the utility of SMYD2 as a prognostic indicator for disease progression." (PMID 36838987, 2023). "SMYD2 is directly activated by the transcription factor MYC, and ablation of SMYD2 impedes the development of leukemia promoted by the fusion oncogene MLL-AF9." (PMID 31370883, 2019). "Transcriptional induction of p21 cell cycle inhibitor in leukemia cells with decreased SMYD2 levels can also account for the observed transient quiescence and more efficient DNA damage response critical for the enhanced survival." (PMID 28187429, 2017). "To investigate the role of the endogenous SMYD2 in leukemia cell proliferation we analyzed the expansion of OCI-AML2 cells infected with shSMYD2 lentiviruses." (PMID 28187429, 2017). "We propose that the interplay between SMYD2 and SET7/9 levels shifts leukemia cells from growth to quiescence state that is associated with the higher resistance to DNA damaging agents and rationalize SET7/9 pharmacological targeting in AML." (PMID 28187429, 2017). "To validate potential mechanisms by which SMYD2 participates in leukemia cells survival/recovery following DNA damage we measured IR-induced cell death upon SMYD2 knockdown." (PMID 28187429, 2017). "As the role of SMYD2 in leukemia cells growth and regeneration remains largely unexplored we decided to focus on this candidate." (PMID 28187429, 2017). "We propose that the interplay between SMYD2 and SET7/9 KMTs levels shifts leukemia cells from growth to quiescence state that is associated with the higher resistance to several DNA damaging agents." (PMID 28187429, 2017). "In correlation with the enlarged quiescent fraction upon SMYD2 knockdown we detected elevated levels of p21 mRNA and protein - observation consistent with its role in regulation of leukemia cells quiescence." (PMID 28187429, 2017). "Induction of the transient dormancy in leukemia cells upon SMYD2 downregulation correlated with the increased DNA damage resistance, but make cells vulnerable to SET7/9 methyltransferase-specific inhibitor." (PMID 28187429, 2017). "Our results using cell lines revealed the involvement of SMYD2 in regulation of leukemia cell growth, survival and regeneration after genotoxic stress." (PMID 28187429, 2017). "In conclusion, we revealed that SMYD2 levels regulate leukemia cell proliferation and response to genotoxic stress." (PMID 28187429, 2017). "The Smyd2 gene was directly activated by the oncogenic transcription factor Myc in either MLL9-AF9-induced leukemias, Myc-induced lymphomas, or fibroblasts." (PMID 27655694, 2016). "On the other hand, Smyd2 deletion from HSCs significantly delayed the progression of MLL-AF9 induced leukemia, Smyd2-deleted leukemic cells showing a substantial competitive disadvantage relative to control cells." (PMID 27655694, 2016). "Based on high expression levels, the function of SMYD2 may contribute to the development and progression of leukemias including CML, ALL, B-ALL, MLLr-B-ALL, AML, and T-ALL." (PMID 36838987, 2023).
leukemia (continued). "The disruption of hematopoietic stem cell transcription and altered Wnt signaling, by way of β-catenin, may interfere with differentiation and contribute to the development of leukemias, implicating SMYD2 as an oncogene." (PMID 36838987, 2023). "When SMYD2 is downregulated, leukemia cells transition to a quiescent state after anti-leukemia chemotherapy treatment, resulting in increased resistance to anticancer drugs, which is thought to be due to increased SET7/9 expression in response to decreasing SMYD2 levels." (PMID 34201935, 2021). "Third, while our recent work established SMYD2 as an important mediator in leukemias, the specific mechanisms by which it directs apoptosis in HSCs and downstream progenitor pools remain unclear." (PMID 32408548, 2020). "Of particular note, global SMYD2-knockouts (KO) in zebrafish have revealed severe developmental defects; however, mice lacking SMYD2 exhibited no severe developmental phenotypes or life-span defects and in fact gained a reduced susceptibility to leukemias." (PMID 32408548, 2020). "Indeed, careful examination of the cell cycle distribution revealed strongly elevated quiescent (G0) and reduced S phase compartments in leukemia cells with decreased SMYD2 levels." (PMID 28187429, 2017). "Transient leukemia cell growth arrest upon SMYD2 downregulation followed by the return to the normal proliferation rate can indicate activation of the compensatory mechanisms in response to changes in the SMYD2 levels and/or activity." (PMID 28187429, 2017). "To explore whether physiological regulators of leukemia cells quiescence, such as growth factors, can affect SMYD2 expression we utilized a growth-factor-dependent AML-193 leukemia line." (PMID 28187429, 2017). "Ablation of Smyd2 did not affect hematopoiesis, but retarded the development of leukemia promoted by MLL-AF9, a fusion oncogene associated with acute myeloid leukemia (AML) in humans." (PMID 27655694, 2016). "Given these complexity, multiple rather than a single SMYD2 target might be implicated in its effect on leukemia cell growth." (PMID 28187429, 2017). "An SMYD2 knockout in MLL-AF9-induced leukemias resulted in dormancy of primary leukemia cells and decreased progression of the malignancy while not impacting hematopoiesis." (PMID 36838987, 2023). "To evaluate whether changes in SMYD2 levels are significant factor in determining primary AML drug sensitivity and patient survival we utilized leukemia patient derived samples." (PMID 28187429, 2017). "However, unlike leukemias, the development of lymphomas was not dependent upon Smyd2." (PMID 27655694, 2016).
cervical cancer (8 papers, 2019 to 2024). A primary or metastatic malignant neoplasm involving the cervix. "Herein, our study demonstrated that the expression of SMYD2 in patients with cervical cancer was associated with FIGO stage, tumor size and correlated with poor prognosis." (PMID 31548876, 2019). "Collectively, these results revealed that SMYD2 was associated with the poor prognosis of cervical cancer patients." (PMID 31548876, 2019). "Herein, our study demonstrated that the expression of SMYD2 in patients with cervical cancer was associated with FIGO stage, tumor size and further correlated with poor prognosis." (PMID 31548876, 2019). "Through immunohistochemistry, the association between SMYD2 expression and clinical-pathological features of cervical cancer patients was further evaluated." (PMID 31548876, 2019). "SMYD2 overexpression is associated with the proliferation and poor prognosis of human non-papillomavirus-related head and neck cancer tumor cells, cell proliferation of esophagus and squamous cell carcinoma, and the incidence of cervical cancer." (PMID 35668081, 2022). "In cervical cancer, SMYD2 expression is correlated with the Federation of Gynecology and Obstetrics (FIGO) stage, tumor size, and poor prognosis." (PMID 39482529, 2024). "Over the past several decades, extensive research has shed light on the pivotal role of SMYD2 in various cancer types, including lung adenocarcinoma, cervical cancer, triple-negative breast cancer, and pancreatic ductal adenocarcinoma." (PMID 39440063, 2024). "Inhibition of SMYD2 expression has been shown to significantly reduce cervical cancer proliferation in vivo and in vitro." (PMID 35498536, 2022). "Our study confirmed a methyltransferase, SMYD2, was involved the development of cervical cancer, and this means of regulation is most likely achieved by influencing transcription of downstream genes." (PMID 31548876, 2019). "We therefore provide a novel therapeutic target, SMYD2, which has a good prospect on cervical cancer treatment." (PMID 31548876, 2019). "In view of the influence of SMYD2 on cervical cancer, the downstream regulation mechanism needs further study." (PMID 31548876, 2019). "To further explore the mechanism of SMYD2 affecting cervical cancer, we used SMYD2-targeted shRNA to inhibit its expression in two types of cervival cancer cells including Siha and Caski cells." (PMID 31548876, 2019). "Cervical cancer is the most common gynecological malignancy with low terminal cure rate, and SMYD2 is highly expressed in multiple tumors and affects their occurrence and development." (PMID 31548876, 2019). "Since previous results suggested the potential effects of SMYD2 on the proliferation of cervical cancer in vivo, we next further explore the role of SMYD2 in the growth and development of cervical cancer in mice." (PMID 31548876, 2019). "On this basis, we then examined the effect of SMYD2 on proliferation of cervical cancer cells performing colony formation and MTT assays." (PMID 31548876, 2019). "In this study, both the TCGA data and our finding confirmed that SMYD2 was positively correlated with poor prognosis of the patients with cervical cancer." (PMID 31548876, 2019). "To further clarify the role of SMYD2 in proliferation of cervical cancer cells in vitro, we examined the expression level of Ki67 and PCNA, respectively." (PMID 31548876, 2019). "We first found a high expression of SMYD2 in cervical cancer, and survival analysis found that the poorer survival rate in the SMYD2 high expression group than that in the low expression group." (PMID 31548876, 2019). "The staining intensity of SMYD2 in clinical samples from 85 cervical cancer patients was then detected." (PMID 31548876, 2019).
cervical cancer (continued). "A total of 306 cervical cancer cases of TCGA patients were analyzed, and the median SMYD2 mRNA expression was used as the cutoff point to divide all the patients into high and low expression groups according to the median." (PMID 31548876, 2019). "SMYD2, as an oncogene, is abnormal highly expressed in multiple types of tumors and further affects the occurrence and development, but the potential correlations between SMYD2 expression and cervical cancer progression is still unclear." (PMID 31548876, 2019). "We first used the bioinformatics website to screen the data of cervical cancer in (The Cancer Genome Atlas) TCGA and survival analysis was used to find the different survival rates in the SMYD2 high expression group and low expression group." (PMID 31548876, 2019). "In this study, we found that SMYD2 was related to the poor prognosis of patients with cervical cancer and regulated the proliferation of cervical cancer." (PMID 31548876, 2019). "In this study, we found that SMYD2 is closely related to cervical cancer and further confirmed its regulatory effect on the proliferation of cervical cancer cells." (PMID 31548876, 2019). "SMYD2 ablation in cervical cancer cells Caski and Siha obviously inhibited cell proliferation and suppressed tumor formation in vivo." (PMID 31548876, 2019). "In cervical cancer, SMYD2 enhanced cell proliferation, contributing to cancer growth." (PMID 35668081, 2022). "Taken together, this study provides strong evidence of the involvement of SMYD2 in cervical tumor growth and indicates that it could have high potential as a therapeutic target of cervical cancer." (PMID 31548876, 2019). "Data showed that inhibition of SMYD2 expression in cervical cancer cell line Caski and Siha could dramatically block the proliferation of cervical cancer cells." (PMID 31548876, 2019). "We first used the bioinformatics website to screen the data of cervical cancer in TCGA and found the high expression of SMYD2 in cervical cancer, and survival analysis found that the poorer survival rate in the SMYD2 high expression group than that in the low expression group." (PMID 31548876, 2019). "Our data further showed that the inhibition of SMYD2 expression in cervical cancer cell line Caski and Siha could dramatically block the proliferation of cervical cancer cells." (PMID 31548876, 2019). "Taken together, this study provides strong evidence of the involvement of SMYD2 in cervical cancer growth and indicates that it could have high potential as a therapeutic target of cervical cancer." (PMID 31548876, 2019). "Therefore, all these data showed that SMYD2 was important in the regulation of cervical cancer proliferation." (PMID 31548876, 2019). "SMYD2, in addition, was found to be associated with FIGO stage and tumor size of cervical cancer." (PMID 31548876, 2019). "Although numerous studies had confirmed the critical role of SMYD2 in the development and progression of tumors, there were few reports on whether SMYD2 affected cervical cancer progression." (PMID 31548876, 2019). "A remarkably downregulated of ki67 and PCNA was found in SMYD2 depleted cervical cancer cells." (PMID 31548876, 2019). "Additionally, SMYD2-shRNA lentivirus infected remarkably inhibited tumorigenesis of cervical cancer cells in mice compared with the scramble group." (PMID 31548876, 2019). "Meanwhile, obvious low expression of SMYD2 was detected in adjacent tissues, providing evidences that SMYD2 could play a key role in the growth and development of cervical cancer." (PMID 31548876, 2019). "We also investigated the prognosis of cervical cancer patients in these two groups, and found that SMYD2 low-expression patients had higher overall survival rate and disease-free survival rate, compared with SMYD2 high-expression groups." (PMID 31548876, 2019). "We also found the similar result in cervical cancer that SMYD2 could further affect tumor development by affecting the proliferation of tumor cells." (PMID 31548876, 2019).
cervical cancer (continued). "Interestingly, the expression of SMYD2 in the cervical tumors was remarkably associated with FIGO stage and tumor size (P < 0.05, respectively), indicating a potential relationship between SMYD2 and cervical cancer." (PMID 31548876, 2019). "Therefore, SMYD2 could represent as a potential and novel therapeutic target for the treatment of cervical cancer." (PMID 31548876, 2019). "Indeed, based on findings in cervical cancer cell lines and our own data (not shown, manuscript forthcoming), Smyd2 induction in response to reductions in physical activity is likely linked to changes in the way glucose and glucose‐products are handled by skeletal muscle." (PMID 39609254, 2024).